ALDH1A1 (aldehyde dehydrogenase 1 family member A1)
Diseases named in the same sentence as ALDH1A1 in open-access papers (continued):
Sharing a sentence is not in itself a finding about the gene and the disease.
tumor (continued). "In conclusion, ALDH1A1 and IGFBP1 are differentially overexpressed in CLM and may play a dual role, functioning as both tumor suppressors and metastasis promoters in CRC." (PMID 27152521, 2016). "We found ALDH1A1 to be expressed very heterogeneously and non-uniformly within the tumor tissue of the HCC specimens." (PMID 26160842, 2015). "At the same time, greater tumor size and higher expression of HER2 in the ALDH1A1 positive group could be found in the subgroup studies with cutoff values >0% or 1%." (PMID 24938375, 2014). "In parallel, upon RUNX2 knockdown, we have observed a predominant and strong downregulation of gene nodes known to be implicated in EOC tumorigenesis (PTGS1/COX1, FGF2, IL1A, Sapk, C/ebp, SELE, UBQLN1, PSAT1, ALDH1A1, GDF15, MTHFD2), including EOC tumor invasion/metastasis (MMP1, MMP13, Creb);." (PMID 24124450, 2013). "The top differentially expressed transcripts between tumor and non-tumor were TPX2, DCBLD2 and ANLN which were significantly increased in tumors (T∶N ratio>2.0, P<0.01), and CDO1, DPEP1, C7, ALDH1A1 and NR3C2 which were significantly decreased in tumors (T∶N ratio<0.2, P<0.01)." (PMID 22363658, 2012). "ALDH1A1 is involved in cellular detoxification and retinoic acid signaling, which may contribute to immune modulation, while HADHA's role in fatty acid β-oxidation influences tumor microenvironment reprogramming." (PMID 40861812, 2025). "To first test that ALDH1A3 can generate atRA in tumor cell lines, we took advantage of the finding that the ALDH1A3-negative cell line MCF7 was sensitive to atRA, and therefore, we ectopically expressed ALDH1A3 along with the related isoforms ALDH1A1 and ALDH1A2 to create stable MCF7 cell lines." (PMID 41210994, 2025). "The association between c-MYC and ALDH1A1 positivity and favorable prognosis of ITAC suggest that rather than having a role in stemness, these factors act as tumor suppressors and may be used as markers of prognosis and response to treatment in ITAC patients." (PMID 41463190, 2025). "This suggests that, in the absence of immunity, ALDH1A1 influences tumor growth by regulating LDHA." (PMID 39107297, 2024). "ALDH1A1, through the ZBTB7B-glycolysis pathway, instigates the excessive accumulation of lactic acid in the tumor microenvironment, culminating in the diminution of anti-tumor immune cell infiltration in the tumor tissue and, consequently, amplifying tumor immune escape." (PMID 39107297, 2024). "After complete tumor resection, ROI-based radio-pathological correlation analyses of the post-therapeutic specimen revealed increased values on the Ktrans-map in vital tumor parts, characterized by cells positive for MIB1- and ALDH1A1, compared to necrotic tumor parts." (PMID 37910565, 2023). "Tumor-spheres in Lu99 cells expressed ALDH1A1, Nanog, Oct4, and Sox2 genes, but not CD133." (PMID 36551502, 2022). "However, mRNA expression of ALDH1A1 indicated a significant reduction in tumor tissues rather than normal tissues by GEPIA2 tool analysis." (PMID 35090523, 2022). "The in vitro assays, however, do not take into account potential sources of Dkk-1, Aldh1a1 or other stress response agents derived from the tumour stroma which may not be targeted by DkkMo." (PMID 35277659, 2022). "Finally, we elucidated the important but overlooked role of ALDH1A1/B1 in tumor-infiltrating lymphocytes (TILs), and we revealed a non-negligible immune regulatory role of ALDH1A1/B1 by drawing gene expression heat maps." (PMID 35280765, 2022). "Furthermore, 79.3% (69/87) of the main tumor body samples showed negative/low expression of ALDH1A1." (PMID 35860042, 2022). "Interestingly, although there was a modest correlation between case identity and LCSC marker group status, we observed that the LCSC marker group 2 cells, which concurrently expressed EPCAM, ALDH1A1, and CD24, grouped together into cell cluster and contained HCC tumor cells from multiple cases." (PMID 34140495, 2021).
tumor (continued). "ALDH1A1 protein expression was heterogeneous and did neither correlate with oncRAS induction at the precursor stage, nor with induction at full-blown tumor stage." (PMID 34172934, 2021). "In addition, EGCG + GTE inhibited AXL activation in tumours, which possessed lower levels of ALDH1A1 and SLUG proteins than those of the non-treated group." (PMID 32051483, 2020). "In addition to ALDH1A1, it is noteworthy that ALDH3A1 was demonstrated to be overexpressed in LUAD compared to normal alveolar cells, the most likely cells of origin/stem cells of this tumor." (PMID 31001473, 2019). "In addition, ALDH1A1 was highly expressed in CRC tumor tissue whereas normal colon tissue was mainly negative." (PMID 30308036, 2018). "Moreover, the ALDH1A1 mutants that retained their GSH/DHLA-dependent NAD+ reduction activity but lost their aldehyde-dehydrogenase activity were able to decrease the NAD+/NADH ratio and to rescue the impaired growth of ALDH1A1/3A1 double knockout tumor cells." (PMID 28978015, 2017). "Similarly, up-regulation of stemness-related genes (ALDH1A1, Nanog, Nestin, Bmi1, and Oct4) was observed in HCC87/gef cells, implying that these gefitinib-resistant cells contained a larger population of tumor-initiating cells." (PMID 25871388, 2015). "However, Aldh1a1 downmodulation in AhR-expressing B16F10 cells did not significantly affect tumor growth in vivo." (PMID 26242870, 2015). "By immunohistochemistry ALDH1 was highly expressed in these tumours, however the antibody we used might not be entirely specific to the isoform ALDH1A1." (PMID 24252471, 2013). "ALDH1A1 status was significantly correlated with strong malignant proliferative marker Ki67 staining (P = 0.001), and no significantly different expression of ALDH1A1 across the subtypes of ER, PR, and HER2 expression and triple negative features of tumor tissue." (PMID 23767668, 2013). "Moreover, using ALDH1A1 mutants that retained this GSH/DHLA-dependent NAD+-reduction activity but lost the aldehyde dehydrogenase activity, we found that ALDH1A1 can decrease the cellular NAD+/NADH ratio and promote tumor growth in xenograft models via the GSH/DHLA-dependent NAD+-reduction activity." (PMID 28978015, 2017). "However, tumor size in the America-Europe subgroup is not related to ALDH1A1 expression." (PMID 24938375, 2014). "While an ALDH1A1 antagonist is not yet FDA-approved for tumor treatment, its potential as a significant anti-tumor drug, synergistically enhancing immunotherapy efficacy, makes it a promising avenue for future research." (PMID 39107297, 2024). "Their trend of expression showed most of them to be upregulated in the tumor samples, regardless of the disease stage, while only PPL, ALDH1A1, GSTA1, TJP3 and CRYAB were downregulated in HNSCC." (PMID 37686696, 2023). "In CRC tumour tissue, CSN6 and TRIM21 showed a significant negative correlation in staining intensity, while CSN6 and ALDH1A1 showed a significant positive correlation in staining intensity." (PMID 32225170, 2020). "Expressions of ABCG2, ALDH1A1, and ALDH3A1 were negatively related with immune infiltration level in HCC, and showed no relation with tumor purity." (PMID 32184801, 2020). "We showed that the expression of CSC markers, such as CD133 and ALDH1A1, and activation of STAT5, were much lower in the tumor of IL-32γ Tg mice as compared with the non-Tg mice." (PMID 31263095, 2019). "Most of these genes, including ADH1B, ALDH1A1, ADH1C and ALDH2, were significantly down-expressed in ER+ or ER- tumors compared to tumor-adjacent normal tissues, although none showed significant differential expression by alcohol intake in either tissue type." (PMID 28899409, 2017). "In our study, we found that ALDH1A1 expression was higher for receptor-positive, low-grade, and non-basal like TNBC tumor tissue." (PMID 26462023, 2015). "CA-IX expression did not correlate with ALDH1A1, CD133, or CD15 staining quantified in the same tumor areas of serial sections." (PMID 24500694, 2014).
tumor (continued). "Sorafenib treatment of HepG2 tumours slightly increased the expression of ΑFP, while sorafenib treatment of stem‐like tumours reduced the expression of CD133 but did not induce a significant modification of AFP or ALDH1A1." (PMID 30959553, 2019). "However, when we measured tumor growth of these cells with deleted ALDH1A1 and/or ALDH3A1, we found that knocking out either gene alone did not inhibit tumor growth." (PMID 28978015, 2017). "Having established that both ALDH1A1 and ALDH3A1 possess the GSH/DHLA-dependent NAD+-reduction activity, we tested whether or not this activity is responsible for the tumor-promoting effects observed for ALDH1A1/3A1." (PMID 28978015, 2017). "Aldehyde dehydrogenase family 1 member A3 (ALDH1A3) not ALDH1A1, was found to correlate most strongly with ALDEFLUOR-positivity and, using immunofluorescence (IF) in primary tumours, was also found to correlate with metastasis and tumour grade." (PMID 22112299, 2011).
adenocarcinoma (20 papers, 2008 to 2025). A common cancer characterized by the presence of malignant glandular cells. "Among adenocarcinomas, the downregulation of ALDH1A1 tended to be more significant in high-grade, poorly differentiated tumors, and tumors with a stronger proliferating activity." (PMID 35814382, 2022). "In adenocarcinoma, the downregulation of ALDH1A1 is often more significant in high-grade, poorly differentiated tumors and tumors with stronger proliferative activity." (PMID 36484016, 2022). "Thus, in this study, the cytotoxicity of a subset of adrenoceptor blockers exhibiting varying selectivity toward adrenoceptors was examined against NSCLC adenocarcinoma cell lines A549 and H1299, cells expressing high and low levels of ALDH1A1, respectively." (PMID 37886948, 2023). "Thus, in this study, we used NSCLC adenocarcinoma cell lines: A549 and H1299 cells expressing high and low levels of ALDH1A1, respectively." (PMID 37886948, 2023). "ALDH1A1 was remarkably downregulated in adenocarcinomas and large cell cancers." (PMID 35814382, 2022). "In this context, initial studies have shown that the ALDH isozymes, ALDH1A1 and ALDH3A1, are expressed in putative epithelial stem cell niches, overexpressed in NSCLCs (both adenocarcinomas and squamous cell carcinomas) compared to normal lung tissue." (PMID 30060526, 2018).
benign tumors (8 papers, 2010 to 2024). "The expression level of ALDH1A1 was significantly lower in SOC tissues compared to benign tumors and normal tissue samples." (PMID 35090523, 2022). "However, lower expression of ALDH1A1 was evident in SOC samples rather than benign tumors and normal tissues." (PMID 35090523, 2022).
infection (8 papers, 2010 to 2025). The state of being infected such as from the introduction of a foreign agent such as serum, vaccine, antigenic substance or organism. "Q-PCR analysis revealed a significant decrease in mRNA of ALDH1A1 (~ 83% reduction) caused by shRNA(-ALDH1A1) infection compared to scrambled shRNA-infected cells." (PMID 37644186, 2024). "ALDH1A1-positive cells were increased in T3 or TRα1 GOF conditions compared to untreated control-infection cells, and further increased in T3-treated TRα1 GOF spheroids." (PMID 38693105, 2024). "Several genes involved in RA metabolic processes, which are known to be inducible by RA, were significantly downregulated in the colon of the VAS mice during peak infection, including Aldh1a1, Aldh1a2, Cyp26b1, and Lrat." (PMID 35458125, 2022). "We observed a pronounced reduction in the number of tumorspheres in the Ad-VP3 group, and a time-dependent decrease in the expression of the stemness markers ALDH1A1, KLF4, and Sox2 at 48 and 72 h post-infection." (PMID 41472305, 2025).
metabolic disorders (5 papers, 2013 to 2022). "ALDH1A1 is an important enzyme associated with metabolic diseases, which catalyzes the second and irreversible step of retinaldehyde oxidation to vitamin A (retinoic acid)." (PMID 34096467, 2021).
inflammation (1 paper, 2022). Aberrant reaction of the microcirculation characterized by movement of fluid and leukocytes from the blood into extravascular tissues. "Our previous study found that Tet1 deletion enhanced HDM-induced lung inflammation in mice, and that it was linked to transcriptomic changes in proinflammatory molecules (Il33) and detoxification enzymes (Gsto1 and Aldh1a1) in total lung RNA." (PMID 35627266, 2022).
neurodegenerative disease (1 paper, 2021). A disorder of the central nervous system characterized by gradual and progressive loss of neural tissue and neurologic function. "Aldehyde dehydrogenase family 1 (ALDH1A1), with reduced mRNA and protein levels in the SN of patients with PD, is associated with the progressive neurodegenerative disease." (PMID 34483877, 2021).
systemic respiratory diseases (1 paper, 2025). "This suggests that, while genomic variants may not yet be linked, downregulation of ALDH1A1 may lead to impaired MCC, contributing to the pathogenesis of these respiratory diseases." (PMID 40408364, 2025).
ALDH1A1 also shares sentences with these, for which no sentence is quoted: head and neck cancer (21 papers); inflammatory breast carcinoma (6); invasive breast carcinoma (6); dysplasia (5); leukoplakia (5); multiple myeloma (5); oral epithelial dysplasia (5); clear cell carcinoma (4); metastasis (4); small cell lung carcinoma (4); Alzheimer disease (3); benign breast disease (3); benign ovarian tumors (3); ductal carcinoma in situ (3); endometrioid adenocarcinoma (3); kidney cancer (3); lichen planus (3); liposarcoma (3); mucoepidermoid carcinoma (3); neuroendocrine tumors (3); renal cell carcinoma (3); serous carcinoma (3); ulcerative colitis (3); adenoid cystic carcinoma (2); astrocytoma (2); brain tumors (2); breast (2); chronic atrophic gastritis (2); endometrial tumors (2); hematological disease (2).
A further 118 diseases each share a sentence with ALDH1A1 in 2 papers or fewer.